CD4 (CD4 molecule)
Diseases named in the same sentence as CD4 in open-access papers (continued):
Sharing a sentence is not in itself a finding about the gene and the disease.
HIV-1 infection (continued). "The phenotypes as a result of an HIV-1 infection in macrophages differ considerably from those of CD4+ T cells." (PMID 27067385, 2016). "Supporting evidence include reports showing that HIV-1 PR specifically cleaves other serine/threonine kinases, including the NDR1 and NDR1 kinases, receptor-interacting protein kinase 1 (RIPK1), and RIPK2 in CD4+ T cells during HIV-1 infection." (PMID 26982200, 2016). "The vast majority of CD4+ T cell death during acute HIV-1 infection occurs in the gut and thus poly-functional CMI responses at the gut mucosa are likely to significantly reduce CD4+ T cell death." (PMID 27853256, 2016). "Our longitudinal analysis revealed a decrease in both total and naive CD4+ T-cell counts during HIV-1 infection, in line with previous observations." (PMID 27010200, 2016). "In vitro and in NOG/SCID mice, CD4 T cells stably expressing C34-conjugated coreceptors appeared to be resistant to HIV-1 infection by their selective outgrowth during HIV-1 infection." (PMID 27855210, 2016). "This inhibition was highly specific and dependent on positioning of the peptide, as HIV-1 infection was poorly inhibited when C34 was conjugated to the amino terminus of CD4." (PMID 27855210, 2016). "IL-2-secreting CD4+ T cells detected by flow cytometry (FCM) were also significantly reduced during HIV-1 infection." (PMID 27145859, 2016). "ISG induction and HIV-1 infection has been evaluated both in culture cells and primary host cells, including CD4+ T cells and macrophages." (PMID 26849062, 2016). "We show here that NFAT activation by virion-packaged Vpr is responsible for productive and enhanced HIV-1 infection of resting CD4+ T cells." (PMID 27383627, 2016). "Antigen-dependent TCR activation of CD4+ T cells is the most efficient stimulus for productive HIV-1 infection in vivo." (PMID 27990142, 2016). "Our data confirm the presence of an overwhelming predominance of phenotypically Th2-like cells during very advanced (< 200 CD4+ T cells/μl) HIV-1 infection." (PMID 27819062, 2016). "In this study, we found that HIV-1 infection decreases the expression of let-7i in CD4+ T cells by attenuating its promoter activity." (PMID 27145859, 2016). "The strongest correlates of neutralization breadth that emerged in the IAVI cohort study were high viral load, low CD4 T cell count, subtype C HIV-1 infection, and HLA-A*03 genotype." (PMID 27851829, 2016). "It has also been shown that human immunodeficiency virus type 1 (HIV-1) infection not only induces apoptosis, but also mediates necroptosis in the infected primary CD4+ T lymphocytes and CD4+ T-cell lines." (PMID 27750220, 2016). "There is therefore a fine balance between inducing enough of a CD4+ response to provide help to CD8+ cells and inducing too many CD4+ cells, which will increase the pool of target cells for HIV-1 infection." (PMID 27427967, 2016). "Using gene expression microarrays, we analyzed mRNA expression patterns in naive, central memory, and effector memory CD4 T cells from healthy controls, and naive and central memory CD4 T cells from patients with HIV-1 infection." (PMID 27875993, 2016). "Based on these network comparisons, we examined how genetic and epigenetic regulation mechanism affects gastric tumorigenesis, hepatocarcinogenesis, and the progression of HIV-1 infections in CD4+ T cells." (PMID 26897165, 2016). "We and others have demonstrated that CD4 + T cells are the first and predominant target cells for HIV-1 infection in the vaginal epithelium, where few FcR-bearing effector cells other than DCs, particularly LCs, were found." (PMID 27919754, 2016). "For instance, IFI16 was reported to mediate CD4+ T-cell programmed cell death upon HIV-1 infection and caspase-1-containing inflammasome formation upon herpesvirus infection." (PMID 27935834, 2016).
HIV-1 infection (continued). "Because IL-2 is a very important cytokine for maintaining activated CD4+ T cell survival and proliferation, we examined the depletion of CD4+ T cells during HIV-1 infection by both cell morphology and Annexin V staining assay." (PMID 27145859, 2016). "Exposure of LP CD4 T cells to a panel of HAMB resulted in enhanced productive CCR5-tropic HIV-1 infection, similar to our previous results with E.coli." (PMID 26762145, 2016). "It has been shown that Mtb can promote HIV-1 infection by increasing the expression of CXCR4 and CCR5, the two HIV-1 co-receptors and increase the susceptibility of CD4+ T cells to HIV-1 infection through a TLR2-mediated pathway." (PMID 27004401, 2016). "CD4+T cell count is currently a major immunological indicator for classification of HIV-1 infection and initiation of antiretroviral treatment." (PMID 26121491, 2015). "Our study shows that CXCR5+PD-1++ CCR5+ TFH cells were the most permissive CD4+ T cell subset to HIV-1 infection and correlated with the expression of cell surface markers PD-1, CCR5, and CXCR3." (PMID 26034905, 2015). "Selective loss of Th22 cells and a reduction in IL-22 cytokine secretion by CD4 T cells occurred in patients with untreated HIV-1 infection, which was restored in part by ART25." (PMID 26347358, 2015). "PLD1i inhibited CXCR4-tropic HIV-1 infection by nearly 75% in CD4+ T cells from four independent donors." (PMID 26020637, 2015). "PBMC cultures from the elderly contain high percentages of TCM cells that are primary targets for HIV-1 replication but low percentages of naïve CD4+ T cells, which are relatively resistant to HIV-1 infection." (PMID 26452480, 2015). "HIV-1 infection is characterized by CD4+ T cell depletion, CD8+ T cell expansion, and chronic immune activation that leads to immune dysfunction." (PMID 25671429, 2015). "The low levels of CD4 and the presence of restriction factors has led to a consensus view that these cells are relatively insensitive to HIV-1 infection in vivo." (PMID 25809903, 2015). "Monocyte/macrophages facilitate the transmission and establishment of HIV-1 infection to the CD4+ T cells." (PMID 25835530, 2015). "In this regard, Tregs are highly susceptible to CCR5-tropic HIV-1 infection because the CCR5 expression levels on Tregs are higher than those on naive and memory CD4+ T cells." (PMID 25807049, 2015). "Elevated programmed death-1 (PD-1) expression on the surface of CD4+ and CD8+ T cells in HIV-1 infection is associated with T cell exhaustion." (PMID 26713320, 2015). "Collectively, these findings demonstrate a novel and rapid miR-29-mediated antiviral activity of IL-21 that acts through STAT3 in target CD4 T cells to limit initial HIV-1 infection." (PMID 26108174, 2015). "The inability of macrophage exosomes to mediate CD4-independent HIV-1 infection support the notion that HIV-1-loaded exosomes utilize a different route such as clathrin-mediated endocytosis to gain entry into host cells." (PMID 26205405, 2015). "Both of the motifs important for CD4 down-regulation and tetherin antagonism are highly conserved, suggesting that the ability of Vpu to down-regulate tetherin and CD4 is important for establishing HIV-1 infection in new patients." (PMID 26184634, 2015). "Together, these findings suggest for the first time the ability of IL-21 to directly suppress HIV-1 infection in CD4 T cells." (PMID 26108174, 2015). "Previously we have shown that HIV-1 infection of resting CD4+ T-cells co-cultured with CD11c+ myeloid dendritic cells (mDC) produced a population of non-proliferating T-cells with latent infection." (PMID 26362311, 2015). "HIV-1JRFL challenge of mice reconstituted with the PromA-M2 inactive control transduced PBMCs showed acute HIV-1 infection as determined by high pVL, CD4+ T cell depletion and extensive immunodeficiency." (PMID 26441979, 2015).
HIV-1 infection (continued). "The progression of HIV-1 infection is accompanied by depletion of CD4+ T cells, resulting in frequent opportunistic infections and the imbalance of Th1 and Th2 responses leads towards the progression of AIDS." (PMID 25835530, 2015). "For the basic research of HIV-1 infection, in vitro cell culture systems including cell lines and primary human CD4+ T cells have been extensively utilized." (PMID 25807049, 2015). "Taken together, our results demonstrate cleavage of RIPK1 in T cell lines and primary CD4+ T cells during HIV-1 infection." (PMID 26297639, 2015). "For HIV-1 infection, CD4/CXCR4/CCR5+ TZM β-galactosidase reporter target cells were exposed to wild-type or drug-resistant HIV-1 variants (1 ng of p24) together with increasing concentrations of DMSO or CypI—CsA, ALV, or CPI-431-32." (PMID 26263487, 2015). "HSV-2 infection results in the expression and secretion of retinoic acid, which induces the expression of α4ß7 integrin on CD4+ T cells to make them more vulnerable for HIV-1 infection." (PMID 26132818, 2015). "HIV-1 infection usually results in the lysis of the CD4+ T cells, but on rare occasions, these cells can survive long enough to revert back to a resting memory state." (PMID 26405463, 2015). "On this subject, we recently provided evidence that primary CD4+ T lymphocytes infected with HIV-1 release exosomes which activate quiescent human primary CD4+ T lymphocytes which in turn become permissive to HIV-1 infection." (PMID 26502902, 2015). "Loisel-Meyer and colleagues have demonstrated that Glu-1 (Glucose transporter 1) an enhancer glycolysis factor, which is a downstream substrate of AKT/PI3K pathway, can regulate HIV-1 infection in CD4+ T cells." (PMID 25875202, 2015). "The HIV-1 infection is characterized byprofound CD4+ T cell destruction and a marked Th17 dysfunction at the mucosal level." (PMID 26654242, 2015). "We analysed the relationship between miRNA-29 levels and those of well-known virological and immunological markers of HIV-1 infection: plasma viral load and CD4+ T cell count." (PMID 25808800, 2015). "We have demonstrated that in the context of the CCR5-tropic HIV-1 infection the accessory protein Nef is required for peripheral blood CD4+ T cell depletion." (PMID 26169178, 2015). "T cell activation often remains elevated in chronic HIV-1 infection in spite of ART and is linked to a lower rate of CD4 T cell count recovery and higher mortality rates." (PMID 26439007, 2015). "The migration of CD4+ T lymphocytes is inhibited by HIV-1 infection both in vitro and in lymph nodes." (PMID 26500651, 2015). "The high expression of CCR5 and α4β7 on IEL and LPL CD4+CD8+ T cells compared to CD4+ T cells, suggests that the CD4+CD8+ T cells are more susceptible to HIV-1 infection." (PMID 26034905, 2015). "The CD4-CCR5 fusion mimetics demonstrated improved binding to Env trimers, neutralized a wider panel of HIV-1 isolates, and were less efficient in promoting HIV-1 infection in CCR5+/CD4− cells as compared with CD4-mimetics." (PMID 26629902, 2015). "Our results thus suggest that low CD4 and high CXCR4 expression both contribute to the high susceptibility of T cells from the elderly to HIV-1 infection." (PMID 26452480, 2015). "At one-week post-HIV-1 infection, large syncytia composed of fused infected CD4+ T-lymphocytes were detected on the surface of adherent hepatoma cells, but this occurred both in the presence or absence of HCV (data not shown)." (PMID 26263487, 2015). "Those functions aredependent of cytokine profile production, and in particular for HIV-1 infection, abetter quality and protective immune response can be sustained if those polyfunctionalT-helper 1 CD4+ T-cell are present (Ferre etal." (PMID 26602876, 2015). "We report that IL-21 suppresses initial HIV-1 infection in lymphoid CD4 T cells and this antiviral activity was rapid, independent of cytotoxic effector T cells, but requires induction of cell-intrinsic miR-29." (PMID 26108174, 2015).
HIV-1 infection (continued). "Expression of Glut1, a glucose transporter, is also essential for HIV-1 infection of activated CD4+ T cells." (PMID 26020637, 2015). "As HIV-1 infection progresses, the CD4+ T cell population declines slowly and the infected individual becomes progressively more susceptible to certain opportunistic infections and neoplasms." (PMID 26709961, 2015). "To examine the impact of Gag-Pro RC on HIV-1 pathogenesis, we investigated the relationship between Gag-Protease RC and clinical markers of HIV-1 infection (pVL and CD4 T-cell count)." (PMID 26585907, 2015). "The purpose of this study was to evaluate epigenetic modifications in PBMCs and CD4+ cells after HIV-1 infection analyzing three approaches: (i) global DNA- methylation; (ii) qPCR array and (iii) western blot." (PMID 25875202, 2015). "After 48 h of coculture, the infected CD4+ C8166 target T cells lost CD4 expression and died due to HIV-1 infection (second panel)." (PMID 26132818, 2015). "Ex vivo and in vivo models of HIV-1 infection have resulted in important advances defining Nef’s critical role for high levels of viral replication and for CD4+ T cell and thymocyte killing." (PMID 26169178, 2015). "Frailty in HIV-1 infection is strongly correlated with a high viral load and CD4+ T cell decline, whereas lipodystrophy syndrome and fat redistribution are associated with combination antiretroviral therapy." (PMID 26204934, 2015). "Abrogation of IL-21-mediated miR-29 induction on STAT3 blockade coupled with enriched STAT3 binding to putative regulatory sites within MIR29 genes support STAT3 as a positive regulator of miR-29 expression in CD4 T cells during HIV-1 infection." (PMID 26108174, 2015). "This allowed us to study mucosal CD4+ T cells before and after HIV-1 infection in the gut and FRT with special emphasis on TFH cells." (PMID 26034905, 2015). "While acute HIV-1 infection presented with marginal CD4 T-cell depletion in blood and spleen of humanized mice, CD4 T cells were severely depleted in gut lamina propria." (PMID 26108174, 2015). "We found an up-regulation of RSK2 gene expression in the CD4+ T cells at the earliest time-points post-HIV-1 infection, being more evident at 24 hours post infection." (PMID 25875202, 2015). "This is also the case in HIV-1 infections where infected CD4+ T cells are rare outside of this inflammatory setting." (PMID 25933119, 2015). "We conducted this pilot study to examine how IDU affects systemic and mucosal CD4+ T cell depletion and immune activation when superimposed on HIV-1 infection." (PMID 26925299, 2015). "In contrast, we observed significantly more HIV-1 infection of activated primary CD4+ T lymphocytes when T lymphocytes were co-cultured with autologous infected MDM, despite similar amounts of free virus in the co-culture supernatant." (PMID 26186441, 2015). "Together, these findings reveal a novel antiviral IL-21-miR-29 axis that promotes CD4 T-cell-intrinsic resistance to HIV-1 infection, and suggest a role for IL-21 in initial HIV-1 control in vivo." (PMID 26108174, 2015). "Both a person’s age and length of HIV-1 infection are key factors for developing HAND because prolonged infection accompanied by a decline in CD4+ T cell count indicates an increased persistence of the virus in the brain." (PMID 26539167, 2015). "p21 has also been found to be a potent inhibitor of HIV-1 DNA integration, and to be responsible for resistance to HIV-1 infection in primitive hematopoietic cells, activated CD4+ T cells and monocyte-derived macrophages." (PMID 25746435, 2015). "While resting CD4+ T lymphocytes are refractory to HIV-1 infection, exposure to Nef and ADAM17 containing exosomes renders these cells permissive to HIV-1 infection." (PMID 26205405, 2015).
HIV-1 infection (continued). "In individuals with human immunodeficiency virus type 1 (HIV-1) infection, CD4:CD8 lymphocyte ratio is often recognized as a quantitative outcome that reflects the critical role of both CD4+ and CD8+ T-cells in HIV-1 pathogenesis or disease progression." (PMID 26191056, 2015). "To understand the effects of HIV-1 co-infection on these morbidities, we examined S. mansoni ultrasound-detectable morbidities in relation to HIV-1 infection and CD4+ cell counts, and other factors in fishing communities where the two infections are present." (PMID 25948238, 2015). "In terms of the condition of human CD4+ T cells, we can say that these two humanized mouse models are the best choices to reproduce and investigate the dynamics of HIV-1 infection in vivo (i.e., under the physiological condition) at present." (PMID 25807049, 2015). "Since CCR5 was identified as the primary HIV-1 co-receptor and the CCR5Δ32 CD4+ T cells were found to be resistant to HIV-1 infection, the reduction or elimination of CCR5 expression have been pursued." (PMID 26588898, 2015). "Gold nanoparticles have also been previously shown to inhibit HIV-1 infection through binding the surface viral glycoprotein (gp120) and inhibiting its attachment with CD4 cells." (PMID 25533100, 2015). "APOBEC3G (A3G) belongs to the apolipoprotein B mRNA editing enzyme catalytic polypeptide-like (APOBEC) family of proteins and was initially identified as a potent restriction factor against HIV-1 infection in human CD4+ T cells." (PMID 25762005, 2015). "To determine the efficiency of CXCR4-gRNA/Cas9 modification in providing protection to primary CD4+ T cells against HIV-1 infection, we infected the cells (containing modified CXCR4) with CXCR4-tropic HIV-1NL4-3 and cultured for 7 days." (PMID 26481100, 2015). "HIV-1 infection leads to a progressive decline in the number of peripheral CD4+ T lymphocytes, dysfunctions in thymic T cells, and changes in the number and function of antigen-presenting cells, such as dendritic cells and monocytes." (PMID 25802474, 2015). "Viral infiltration and replication in early HIV-1 infection result in rapid and profound intestinal CD4+ T cell depletion." (PMID 26696749, 2015). "In particular, CCL2, mainly produced by monocytes/macrophages both in vitro and in vivo, recruits CCR2+CD4+ T lymphocytes and monocytes/macrophages, which represent key target cells for HIV-1 infection." (PMID 25608886, 2015). "HIV-1 infection namely reduces the viability of CD4+ T cells, whereas infected macrophages are long-lived." (PMID 26500651, 2015). "Host and viral factors as independent correlates of immunologic health (average CD4:CD8 ratio >1.0) in early HIV-1 infection." (PMID 26191056, 2015). "The intracellular expression of Tat101 protein delays Fas-mediated apoptosis during HIV-1 infection in CD4+ T lymphocytes." (PMID 26376973, 2015). "The consistent immunogenicity across clades suggests the predicted CD4 epitopes are shared to some extent in HIV-1 infection by different subtypes." (PMID 26302050, 2015). "After inhibition or disruption of CXCR4 in primary lymphocytes using siRNA or ZFNs, the CD4+ T lymphocytes became capable of resisting CXCR4-tropic HIV-1 infection." (PMID 26588898, 2015). "We further analysed the role of each gene in HIV-1 infection of DC and CD4+ T-cells using a PubMed search for the interactions between DC and T-cells, and potential roles in the establishment of HIV-1 latency." (PMID 26362311, 2015). "For subjects with CD4:CD8 ratio ≤1.0 soon after HIV-1 infection, we were unable to determine if this was the result of rapid disease progression or low CD4:CD8 ratio before infection." (PMID 26191056, 2015). "Taken together, these results implicate an IL-21–miR-29 axis in direct HIV-1 suppression in CD4 T cells and suggest that pretreatment with IL-21 can limit the magnitude of the initial HIV-1 infection in vivo." (PMID 26108174, 2015).